BRAF (B-Raf proto-oncogene, serine/threonine kinase)
Diseases named in the same sentence as BRAF in open-access papers (continued):
Sharing a sentence is not in itself a finding about the gene and the disease.
melanoma (continued). "Moreover, the vemurafenib-resistant BRAF-mutant melanomas may acquire dependency on the presence of the targeted drug for their proliferation, such that interruption in administering the BRAF inhibitor may lead to regression of non-lethal drug-resistant tumors." (PMID 26322273, 2015). "The in vitro and in vivo activity of LY2090314 in preclinical models suggests that the role of Wnt activators for the treatment of both BRAF and NRAS driven human melanoma should be further explored." (PMID 25915038, 2015). "Univariate analysis showed that BRAF, Dicer, KAI1, P27 and Tip60 were differentially expressed in metastatic melanoma as compared to primary melanoma." (PMID 26246476, 2015). "Among the 779 cases, 150 cases were positive for BRAF (V600E) staining, including 38 cases (of 611, 6%) of CRC, 102 (of 127, 80%) cases of PTC and 10 (of 41, 24%) cases of malignant melanoma." (PMID 25784606, 2015). "At present, whether pulmonary malignant melanomas carry BRAF mutations has not been reported." (PMID 26376781, 2015). "So far, several driver genes including BRAF, NRAS, KIT, GNAQ, and GNA11 have been characterized and routinely used in clinical screenings for melanoma." (PMID 25890285, 2015). "This not only emphasizes the relevance of the BRAF‐MITF link, but also confirms that BRAFV600E co‐operates with appropriate MITF levels in driving melanoma initiation." (PMID 25818589, 2015). "Polyclonal anti-CSPG4-antibodies reduced the Transwell migration of vemurafenib-treated, BRAF V600E-mutant and CSPG4-expressing melanoma cells in hypoxia." (PMID 25997619, 2015). "In a phase II study, conducted by Ascierto and coworkers, the activity against BRAF- and NRAS-mutant melanomas has been proved." (PMID 26171394, 2015). "The characterization and discovery of BRAF mutations in a variety of human cancers has led to the development of specific inhibitors targeting the BRAF/MAPK pathway and dramatically changed clinical outcomes in BRAF-mutant melanoma patients." (PMID 29061943, 2015). "Immediately downstream of RAFs, MEK is one of the main signaling nodes in the MAPK pathway and MEK inhibitors have shown significant growth inhibitory effects in some BRAF and NRAS mutant melanoma cells." (PMID 25645078, 2015). "However, more prolonged interruption of pathway inhibition may provide greater benefits and is being investigated in a clinical trial randomizing patients with advanced BRAF mutant melanoma to continuous or intermittent exposure to dabrafenib and trametinib (NCT02196181)." (PMID 26236691, 2015). "However, RICTOR amplification is always associated with PTEN LOH in BRAF mutated melanoma, suggesting that RICTOR overexpression may not enhance AKT activation in the presence of PTEN in these melanoma." (PMID 26356562, 2015). "Videomicroscopy measurements were used to evaluate the effect of ZA treatment on migration in one BRAF mutant and PTEN wild-type, two BRAF mutant and PTEN-null, two NRAS mutant and two triple wild-type melanoma cell lines." (PMID 25646931, 2015). "Incidentally, several drugs have been developed that treat cancers driven by BRAF, two of which, vemurafenib and dabrafenib, are now FDA approved for treatment of late-stage melanoma." (PMID 26312489, 2015). "Early 2014, FDA approved a combination of BRAF inhibitor (dabrafenib) and MEK1/2 inhibitor (trametinib) for the treatment of late stage malignant melanoma, due to ineffectiveness of vemurafenib monotherapy." (PMID 26497853, 2015). "The dual inhibition of BRAF and MEK is currently one of the most promising therapeutic options to improve survival in melanoma patients." (PMID 26481107, 2015). "Nevertheless melanoma cultures (KMKD) obtained from a patient before and after treatment with the BRAF inhibitor, vemurafenib showed a decrease in levels of EZH2 protein in the treated cells and a decrease in the GSK126 IC50 values." (PMID 26304929, 2015).
melanoma (continued). "However, as S73/S409 are target sites for ERK‐/RSK1‐mediated phosphorylation, assessing the BAC transgenic mice in the context of deregulated MAPK signalling in an NRAS and/or BRAF mutant background will be of major importance and could reveal essential regulatory mechanisms relevant for melanoma." (PMID 25818589, 2015). "In patients with BRAFV600E-positive melanoma enrolled in large randomized phase III studies, treatment with BRAF kinase inhibitors such as vemurafenib and dabrafenib resulted in response rates of over 50–60% and progression-free survival (PFS) of 6–7 months." (PMID 26498143, 2015). "Since then, evidence of melanoma dependency on MAPK pathway accumulated and its inhibition by either BRAF or MEK inhibitors (BRAFi and MEKi, respectively) emerged as a therapeutic strategy." (PMID 26098773, 2015). "For example, the oncogenic V600E bRAF mutation, expressed in the majority of patients with cutaneous melanoma, is thought to be the result of solar ultraviolet exposure and is absent from melanomas occurring in body locations that are naturally protected from ultraviolet radiation." (PMID 26075084, 2015). "BRAF and MEK inhibitors have improved outcomes for patients with BRAF-mutant melanoma, but their efficacy is limited by both intrinsic and acquired resistances." (PMID 26137449, 2015). "Since BRAF and MEK inhibitors have recently shown promise as combination therapy for BRAF-mutant melanoma, the effectiveness of selumetinib and vemurafenib in combination at preventing cell proliferation was also determined." (PMID 26137449, 2015). "BRAF-induced MAPK signaling further induces or activates ERK1/2 activity, thereby regulating cell proliferation, survival, migration and metastasis in melanomas." (PMID 26393652, 2015). "The discovery of the BRAFV600E substitution as the most common genetic event in melanoma rapidly led to the clinical development of selective ATP-competitive RAF kinase inhibitors (i.e. Vemurafenib, Dabrafenib) targeting the mutant BRAF protein." (PMID 25742786, 2015). "BRAF patients were slightly younger than NRAS and WT/WT; mean age at primary melanoma and at LM was respectively 50 ± 16 and 56 ± 16 years for BRAF, 55 ± 22 and 59 ± 20 years for NRAS and 55 ± 12 and 59 ± 11 years in WT/WT patients." (PMID 26305188, 2015). "Combined therapy using both a BRAF inhibitor (PLX4720) and a MEK inhibitor (AZD6244) has demonstrated the ability to overcome resistance to MEK inhibition in metastatic melanoma cell lines." (PMID 25785246, 2015). "The FDA-approved anti-melanoma drug combination of trametinib and dabrafenib is evidenced here by the recognized relationship between the MAP2K1 and BRAF proteins in the MAPK signaling pathway and phosphorylation of its constituent proteins in melanoma tumors." (PMID 26262134, 2015). "Targeted therapies such as the oncogenic BRAF inhibitor PLX4032 (with generic drug name vemurafenib) has resulted in high response rates and improved overall survival in patients with melanoma." (PMID 25939769, 2015). "Our novel findings show that miR-524-5p expression is regulated via the MAPK/ERK pathway and that miR-524-5p functions in a feedback mechanism to inhibit MAPK/ERK signaling through BRAF and ERK2 in melanoma progression." (PMID 25275294, 2014). "In BRAFV600E mutant colorectal cancer cells, which generally express higher levels of EGFR than melanomas, activation of EGFR and downstream pathways occurs in response to vemurafenib and is responsible for resistance towards this BRAF inhibitor." (PMID 24970815, 2014). "GSK2118436 inhibitor and BRAF: Other mutant BRAF inhibitors are also gaining momentum clinically, such as GSK2118436 (Dabrafenib), and are closely monitored in the melanoma field." (PMID 25361007, 2014). "They concluded that BRAF inhibition by PLX-432 led to inhibition of cell proliferation in BRAF-mutant cell lines, but BRAF wild-type (WT) melanoma cell lines were relatively resistant." (PMID 25316614, 2014).
melanoma (continued). "All three (100%) BRAF/NRAS double mutants, 11 of 14 (78%) NRAS mutants and 5 of 7 (71%) wild-type melanomas were sensitive." (PMID 25142146, 2014). "In this study, we perform small RNA profiling and identify miR-146a as an oncogenic BRAF- and NRAS-regulated miRNA that promotes the initiation and progression of melanoma." (PMID 24550252, 2014). "A pooled RNA interference screen targeting >16,500 genes in a BRAF inhibitor-sensitive melanoma cell line identified NF1 as the highest ranking gene whose knockdown abrogated the growth inhibitory effects of PLX4720, a BRAF inhibitor." (PMID 25026295, 2014). "Treatment of BRAF-mutant and NRAS-mutant melanoma lines with WNT3A and the MEK inhibitor AZD6244 induces apoptosis." (PMID 24743024, 2014). "A combination of a BRAF and PI3K inhibitor effectively eliminates BRAF inhibitor-resistant melanoma cell line clones; currently, a clinical trial using vemurafenib and BKM120, a PI3K inhibitor, is ongoing (ClinicalTrials.gov)." (PMID 25538140, 2014). "MeWo (BRAF wildtype, NRAS wildtype), SkMel28 (BRAF V600E mutant, NRAS wildtype), HT144 (BRAF V600E mutant, NRAS wildtype) and UACC62 (BRAF V600E mutant, NRAS wildtype) melanoma cell lines were screened for PTEN protein." (PMID 24830350, 2014). "We found no substantial differences in the levels of ERK1/2, MEK1/2, BRAF, NRAS between the horse and human melanoma cells." (PMID 25413220, 2014). "However, it is not yet clear whether BRAF inhibitors are effective in patients with rare-mutation-positive melanoma." (PMID 25265970, 2014). "The approval of the immune stimulant ipilimumab and the subsequent development of novel targeted agents against BRAF, MEK, and PD-1 have fundamentally changed the landscape of melanoma treatment." (PMID 25062770, 2014). "Accordingly, we find that BRAF and NRAS mutant melanoma cell lines and short-term melanoma cultures show higher levels of miR-146a compared to those that are wild type for these genes." (PMID 24550252, 2014). "An important study demonstrated production of HGF by stromal cells in patients with melanoma, which resulted in activation of the HGF receptor MET, reactivation of the MAPK and PI3K pathways, and resistance to BRAF." (PMID 24743024, 2014). "For instance, Das Thakur and colleagues argued that vemurafenib-resistant melanoma cells exhibit similar resistance to the MEK inhibitor AZD6244, due to elevated BRAF (V600E) expression." (PMID 24634165, 2014). "IGF-1R/PI3K signaling was enhanced in resistant melanomas; combined treatment with IGF-1R/PI3K and MEK inhibitors induced death of BRAF inhibitor-resistant cells." (PMID 24743024, 2014). "The first of these trials has recently opened (NCT01989585) and is a Cancer Therapeutics Evaluation Program (CTEP)-sponsored study of navitoclax in combination with the BRAF inhibitor dabrafenib and the MEK inhibitor trametinib in BRAF-mutant melanoma." (PMID 24983357, 2014). "It appears counter-intuitive that positive BRAF status may be associated with a negative prognosis, if the presence of BRAF mutations in melanoma closely correlates with a younger age of patients, a well-documented positive prognostic factor in stage I–III melanoma." (PMID 24959217, 2014). "We evaluated cell growth in melanoma cell lines after BCL-2/BCL-XL inhibition with ABT-263 and BRAF inhibition with PLX4720 using MTT assays." (PMID 24983357, 2014). "Our in silico significance and proximity analysis of 28 paired cases (13 WGS and 15 targeted cases) identified known (e.g., BRAF, NRAS, CDKN2A, and GRIN2A) and novel (e.g., EPHA3, GRIN2B, and ASXL3) genes involved in melanoma." (PMID 25393105, 2014). "Surprisingly, a reverse treatment study, using a MEK followed by a specific BRAF inhibitor, demonstrated some encouraging results by reporting an increase in TTP (time to progression) in melanoma patients." (PMID 25361007, 2014).
melanoma (continued). "For BRAF and NRAS wild-type melanoma cell lines, all seven were sensitive to ERK inhibition, with six of seven highly sensitive to SCH772984, including M418, which is a KRASG12A mutant." (PMID 25142146, 2014). "Advances in the molecular characterization of melanoma and BRAFV600E mutant protein and better knowledge of the BRAF signaling cascade have enabled the development of therapeutic BRAF-kinase inhibitors that target the constitutively active mutant BRAF protein." (PMID 25265970, 2014). "So far, it has been reported that ERK inhibitors have anti-tumor effects in melanoma xenografts and that ERK inhibition can overcome MEK and BRAF inhibitor resistance." (PMID 25538140, 2014). "We monitored miR-146a expression in a panel of BRAF/NRAS wild-type or BRAF or NRAS mutant melanoma cell lines, short-term patient-derived melanoma cultures and melanocytes." (PMID 24550252, 2014). "These discoveries have led to the development of inhibitors for BRAF and KIT (C-Kit) signaling, some of which have shown benefit in melanoma patients." (PMID 25393105, 2014). "Our largest comprehensive molecular analysis of clinical stage III melanoma revealed that BRAF and NRAS mutational status is not a prognostic marker in stage III melanoma patients with macroscopic nodal involvement, but may have implications for potential adjuvant therapy." (PMID 24959217, 2014). "Together, our data suggest the presence of oncogenic BRAF as determinant of the efficiency of trametinib in CRC cells, an observation that is in line with similar findings in malignant melanoma." (PMID 25309914, 2014). "SCH772984 is highly active amongst BRAF-mutant, NRAS-mutant, double mutant and double wild-type melanoma cell lines, and this drug potently inhibited some lines with innate resistance or acquired resistance to vemurafenib." (PMID 25142146, 2014). "Two of the three lines most sensitive to MIF depletion are BRAF mutants (MelCV and MelRMu) indicating the effects of MIF signalling in melanoma were likely outside this pathway." (PMID 25168062, 2014). "Usp5 knockdown overcame acquired vemurafenib resistance and sensitized BRAF and NRAS mutant melanoma cells to apoptosis initiated by MEK inhibitor, cytokines or DNA-damaging agents." (PMID 24980819, 2014). "Inhibition of BRAF leads to inhibition of glycolytic pathway for ATP production, but MITF-expressing melanomas can undergo a bioenergetics adaptation via MITF-PGC1a-OXPHOS upregulation." (PMID 24743024, 2014). "Because BRAF signals through the MAPK pathway, such a pathway is recognized as relevant in melanoma cell survival." (PMID 24980831, 2014). "However, it is clear that BRAF WT cells also respond to iHsp90s with increased antigen expression, as cells expressing only NRAS mutations, as well as cells that are WT for both of these genes, (such as the human gliomas) and the murine melanoma) all are susceptible to iHsp90 antigen induction." (PMID 25503774, 2014). "As a consequence of these results, vemurafenib was the first oral BRAF inhibitor approved by the food and drug administration (FDA) in 2011 for the treatment of melanoma." (PMID 24920406, 2014). "In melanomas harboring activated BRAF, activation of MEK/ERK is achieved by this isoform, while in melanomas with oncogenic RAS, the activating signal to ERK is passed by the WTCRAF, due to deregulation of its inhibition." (PMID 25413220, 2014). "Noxa was rapidly reduced at both the protein and mRNA levels in BRAFV600E melanoma cells (IgR3 and MM200 cells) after treatment with the mutant BRAF inhibitor PLX4720." (PMID 25365078, 2014). "BRAF testing and targeted treatment in BRAF-mutated melanoma patients is not standard of care in all countries and all clinical practices, and understanding the total-cost economics and health value produced from this treatment strategy may be valuable in guiding future standards." (PMID 25198196, 2014).
melanoma (continued). "It is now accepted that genetic lesions in BRAF and NRAS have different consequences in melanoma formation and it is becoming apparent that BRAF can regulate invasion and metastasis through mechanisms different to NRAS." (PMID 24941944, 2014). "Whereas BRAF only activates the MAPK-pathway, NRAS activates several other effectors including Ral-GDS or PI3-kinase, which is of special relevance for melanoma." (PMID 24941944, 2014). "MET amplification (at 7q21) has been identified as a mechanism of innate resistance to vemurafenib in one melanoma cell line, LM38, opening new possibilities for efficacious combinations of MET and BRAF inhibitors." (PMID 28548075, 2014). "An in vitro study analyzed effects of BRAF and MEK inhibition on function of dendritic cells (DC) in vitro and found that BRAF-mutant melanomas suppress immune function of dendritic cells." (PMID 24743024, 2014). "Caenepeel and colleagues reported that HGF rescued melanoma cell lines,notably SK-MEL-5, from BRAF or MEK inhibition using vemurafenib (an analogue of PLX4720)or PD0325901, respectively, and the rescue was attenuated by MET inhibition." (PMID 25490933, 2014). "A recent study showed that upregulation of Wnt signaling is required for cell death induction in melanoma cells by PLX4720, a selective inhibitor of activated BRAF(V600E)." (PMID 24809668, 2014). "A number of BRAF fusions are, however, novel, including ATG7–BRAF in melanoma, as well as ZC3HAV1–BRAF and FAM114A2–BRAF in thyroid cancer." (PMID 25204415, 2014). "Interestingly, while the combined treatment with PLX4720 and ABT-737 induced apoptosis in melanoma cell lines established from pre-therapy lesions, this effect was lost in cell lines from post-therapy lesions of patients who developed resistance to the BRAF inhibitor." (PMID 24920406, 2014). "Targeted therapy with inhibitors of the BRAF and MKE proteins is well-established for those patients with BRAF-mutant melanoma." (PMID 25593913, 2014). "Vemurafenib and dabrafenib selectively inhibit the v-Raf murine sarcoma viral oncogene homolog B1 (BRAF) kinase, resulting in high response rates and increased survival in melanoma." (PMID 24192036, 2013). "One of the key oncogenic pathways involved in melanoma aggressiveness, development and progression is the RAS/BRAF/MEK pathway, whose alterations are found in most patients." (PMID 24238212, 2013). "The BRAFV600E mutation provides constitutive activation of the MAPK pathway, making it independent of upstream growth factor signaling; however, melanomas with a driver mutation other than the BRAF mutation may be more dependent on growth factors and upstream signaling." (PMID 24047116, 2013). "Three melanoma cell lines were tested: LOX IMVI (BRAF V600E), MST-L (BRAF V600R) and WM266 (BRAF V600D)." (PMID 23890105, 2013). "BRAFV600E mutant and wild-type melanoma cell lines were treated for 24 h with the MEK inhibitor U0126, the BRAF inhibitor vemurafenib, or respective controls (U0124 or DMSO)." (PMID 24194739, 2013). "The best example is represented by the selective BRAF inhibitor vemurafenib, the first FDA-approved targeted drug successfully used on BRAFV600E metastastic melanoma patients." (PMID 23704925, 2013). "This small molecule is a potent inhibitor of mutant BRAF (V600E), wild-type BRAF and c-RAF, in colon, melanoma and thyroid cancer cell lines as well as in xenograft mouse models." (PMID 23617957, 2013). "Conversely, inhibition of Ras, BRAF, or MEK blocks ERK activity and inhibits the growth of melanoma cells both in vitro and in vivo." (PMID 24416617, 2013). "Since preclinical studies indicate that BRAF inhibitors are ineffective in melanomas lacking BRAF mutations and may even enhance growth, advanced clinical trials of vemurafenib and other BRAF inhibitors are being carried out specifically in patients whose melanomas contain BRAF mutations." (PMID 23658559, 2013). "However, the oxidative state of melanoma resistant to BRAF inhibitors is unknown." (PMID 24161908, 2013).